TET1 (tet methylcytosine dioxygenase 1)
Diseases named in the same sentence as TET1 in open-access papers (continued):
Sharing a sentence is not in itself a finding about the gene and the disease.
thyroid cancer (3 papers, 2021 to 2023). "Our work, using thyroid cancer as a model, provides evidence for the oncogenic function switch of TET1 under hypoxia and identifies an underlying mechanism independent of its classical enzymatic activity." (PMID 37020036, 2023). "We next tested the effect of ectopic expression or deletion of TET1 on HIF1α expression in thyroid cancer cells." (PMID 37020036, 2023). "To test this, we cultured thyroid cancer cells in both normoxia (21% O2) and hypoxia (1% O2) and found that ectopic expression of TET1 in 8505C cells did suppress cell proliferation under normoxia, while it promoted cell proliferation under hypoxia." (PMID 37020036, 2023). "These in vitro results indicated that TET1 functioned as a tumor suppressor in thyroid cancer cells, which was consistent with a recent study suggesting that TET1 inhibited thyroid cancer cell migration and invasion." (PMID 37020036, 2023). "This forms a feedback loop in which TET1 promotes thyroid cancer progression via the CK2/AKT/GSK3β/HIF1α signaling pathway." (PMID 37020036, 2023). "Through a series of in vitro and in vivo studies, using thyroid cancer as a model, we demonstrate that TET1 plays a tumor suppressor function in normoxia and, surprisingly, an oncogenic function in hypoxia." (PMID 37020036, 2023). "Collectively, these in vivo findings support a tumor-promoting role of Tet1 in thyroid cancer and suggest that TET1 plays distinct roles in thyroid cancer in vivo versus in vitro." (PMID 37020036, 2023). "In summary, this study demonstrates that TET1 plays distinct roles under in vitro and in vivo conditions in cancer, such as thyroid cancer, which is due to the different oxygen environments; hypoxia switches on its oncogenic functions through HIF1α." (PMID 37020036, 2023). "We ectopically expressed TET1 in thyroid cancer cell lines 8505C and K1 using the doxycycline (dox)‐inducible Tet‐On system and demonstrated that ectopic expression of TET1 upregulated genomic 5-hmC levels compared with the control." (PMID 37020036, 2023). "However, in vitro experiments under normoxia demonstrated that TET1 overexpression suppressed the proliferation, colony formation and migration of thyroid cancer cells, while TET1 knockout produced opposite effects." (PMID 37020036, 2023). "We speculated that HIF1α might mediate oncogenic roles of TET1 in thyroid cancer." (PMID 37020036, 2023). "We knocked out TET1 in thyroid cancer cell line C643 using the lentivirus-mediated CRISPR-Cas9 system and successfully validated TET1 knockout in single-cell colonies by Sanger sequencing, western blot analysis and dot-blot analysis of genomic 5-hmC." (PMID 37020036, 2023). "In our own samples, TET1 expression was clearly downregulated in 17 primary thyroid cancers compared to their paired noncancerous tissues by qRT-PCR and immunohistochemistry (IHC) assays." (PMID 37020036, 2023). "To study the in vivo role of TET1 in thyroid cancer, we generated thyroid-specific Tet1 knockout mouse model by crossing LSL-BrafV600E, LSL-Tet1 and thyroid peroxidase (Tpo)-Cre mice to generate thyroid cancer with various genotypes." (PMID 37020036, 2023).
acute kidney injury (2 papers, 2023 to 2025). Sudden and sustained deterioration of the kidney function characterized by decreased glomerular filtration rate, increased serum creatinine or oliguria. "As a member of the Tet family, the role of Tet1 in acute kidney injury (AKI) remains unclear." (PMID 37908721, 2023).
airway hyperresponsiveness (2 papers, 2019). "Here we used mice deficient for Tet1 in a well-established model of allergic airway inflammation and demonstrated that loss of Tet1 increased disease severity including airway hyperresponsiveness and lung eosinophilia." (PMID 31089182, 2019).
alcoholic liver diseases (2 papers, 2021 to 2023). A disorder caused by damage to the liver parenchyma due to alcohol consumption. "Progression of alcoholic liver disease was linked to TET-1 inhibition and decreased 5hmC formation that promote apoptotic gene expression in hepatocytes." (PMID 37231414, 2023).
allergic asthma (2 papers, 2023 to 2025). A asthma with a basis in a pathological type I hypersensitivity reaction. "In children with allergic asthma, the methylation levels of the TET1 promoter region decrease, resulting in an increase in TET1 expression in bronchial epithelial cells, followed by an increase in the global 5hmC contents." (PMID 40599235, 2025). "In this study, we assessed how knockdown of TET1 and challenge of HBECs with house dust mite extract (HDM, known for its causal role in allergic asthma) affected chromatin accessibility, H3K27ac levels, DNA methylation, and gene expression." (PMID 38168374, 2023). "Overall, TET1 knockdown in HBECs had a very similar overall effect to HDM treatment, reinforcing results from our previous studies indicating that TET1 plays a protective role in allergic asthma and supporting a significant mediatory role for TET1 in responses to HDM." (PMID 38168374, 2023).
Anxiety (2 papers, 2022). Intense feelings of nervousness, tension, or panic often arise in response to interpersonal stresses. "Likewise, Tet1 overexpression affects adult hippocampal neurogenesis and Tet1-transgenic mice showed elevated anxiety and enhanced fear memories." (PMID 35563298, 2022). "Deleted Tet1 in NAc increased the anti-anxiety-like effect in mice." (PMID 36672612, 2022).
atherosclerosis (2 papers, 2022). A disease characterized by the build-up of fatty material and calcium deposition in the arterial wall resulting in partial or complete occlusion of the arterial lumen. "Second, aberrantly increased expression of TET1 in vascular endothelial cells has been linked to human atherosclerosis." (PMID 35344434, 2022). "Given that TET1s is the predominant transcript of TET1 in somatic tissue and epigenetic modification plays an important role in atherosclerosis development, we postulated that TET1s is the true mediator of this process." (PMID 35342333, 2022). "TET1 is also enriched in endothelial cells and mediates atherosclerosis development through epigenetic modification." (PMID 35342333, 2022). "To investigate the function of TET1 in atherosclerosis, we first introduced the structure of the TET1 gene and tested the expression of TET1-FL and TET1s in ECs from C57BL/6 mice with whole aortas." (PMID 35342333, 2022). "We also show that TET1s can significantly delay the development of atherosclerosis by comparing two different knockout mice, ApoE-/-TET1-/- and ApoE-/-TET1cs/cs." (PMID 35342333, 2022). "Although TET1 may participate in atherosclerosis development, the precise role of TET1 in OSS-induced atherosclerosis is unclear." (PMID 35342333, 2022).
autoimmune disease (2 papers, 2024 to 2025). A disorder resulting from loss of function or tissue destruction of an organ or multiple organs, arising from humoral or cellular immune responses of the individual to their own tissue constituents. "Beyond oncology, TET1 exerts significant influence in diverse areas, including cardiovascular diseases, autoimmune disorders, inflammatory conditions, reproductive and developmental anomalies, metabolic imbalances, and neurological dysfunctions." (PMID 40520993, 2025). "TET1 plays a critical role in autoimmune diseases by regulating the function and differentiation of regulatory T cells, which are essential for immune homeostasis." (PMID 40520993, 2025). "In another study conducted in 2022, TET1's role in autoimmune disease was investigated in the context of systemic sclerosis." (PMID 40520993, 2025). "Loss of TET1 and TET2 leads to hypermethylation of Foxp3, impairing regulatory T cell differentiation and function, ultimately contributing to the development of autoimmune diseases." (PMID 40520993, 2025).
bone cancer (2 papers, 2023 to 2024). A primary or metastatic malignant neoplasm affecting the bone or articular cartilage. "We found that the TRPV4 inhibitor (HC067047) significantly relieved bone cancer pain, which causes overexpression of TET1 and TRPV4, and that inhibition of TET1 reduces TRPV4 expression." (PMID 37190609, 2023). "In L4–6 DRG, TET1 was found in the cytoplasm and nucleus, and it was presumed to potentially enhance the progression of bone cancer pain through nuclear translocation to modulate gene expression through DNA demethylation processes." (PMID 38730655, 2024). "In summary, the study suggests that TET1 contributes to bone cancer pain by upregulating TRPV4 expression in the L4–6 DRG of rats." (PMID 37190609, 2023). "In this study, we successfully established a rat model of bone cancer pain and found higher expression of the demethylase TET1 in L4–6 DRG." (PMID 37190609, 2023). "To verify whether TET1 or TRPV4 regulates bone cancer pain, we respectively injected the TET1 inhibitor Bobcat339 and TRPV4 inhibitor HC067047 intrathecally into BCP rats." (PMID 37190609, 2023). "This suggested that the TET1 inhibitor may be a potential drug for the treatment of bone cancer pain." (PMID 37190609, 2023). "This suggested that TET1 was specifically highly expressed in bone cancer pain compared to TET2." (PMID 37190609, 2023). "Interestingly, with the use of the TET1 inhibitor for seven consecutive days, as the bone cancer pain was relieved, the expression of TET1 itself was followed by a decrease." (PMID 37190609, 2023). "Therefore, we examined the expression changes of TRPV4 after intrathecal administration of TET1 inhibitors to rats with bone cancer pain." (PMID 37190609, 2023). "Therefore, we hypothesized that TET1 promotes the development of bone cancer pain by translocating to the nucleus to exert DNA demethylation." (PMID 37190609, 2023). "Therefore, we suggested that TET1 may contribute to bone cancer pain by upregulating TRPV4 expression in BCP rats." (PMID 37190609, 2023). "However, whether and how TET1 contributes to bone cancer pain in the rat DRG remains unclear." (PMID 37190609, 2023). "We found that TET1 expression was increased in BCP rats, and the TET1 inhibitor relieved bone cancer pain and decreased TRPV4 expression." (PMID 37190609, 2023). "According to qPCR results, TET1 and TRPV4 mRNA levels gradually increased after the onset of bone cancer pain compared to those in the sham group, but TET2 mRNA levels remained constant over time." (PMID 37190609, 2023). "As far as we know, this study was the first to show that TET1 inhibition downregulated TRPV4 expression and alleviated bone cancer pain in rats." (PMID 37190609, 2023). "However, whether TET1 is involved in bone cancer pain remains unclear." (PMID 37190609, 2023). "In another study focusing on CIBP, researchers sought to investigate whether a demethylase named TET1, previously discovered to be overexpressed in the DRG of female rats with bone cancer pain, also contributed to the upregulation of TRPV4 expression." (PMID 38730655, 2024). "As a result, these findings suggested that TET1 may contribute to bone cancer pain by upregulating TRPV4 expression in the L4–6 DRG of BCP rats and that TET1 or TRPV4 may become therapeutic targets for bone cancer pain." (PMID 37190609, 2023). "In this study, we hypothesized that TET1, a demethylase elevated in the DRG of rats with bone cancer pain, upregulates TRPV4 expression." (PMID 37190609, 2023).
chronic myelomonocytic leukemia (2 papers, 2020 to 2021). A myelodysplastic/myeloproliferative neoplasm which is characterized by persistent monocytosis, absence of a Philadelphia chromosome and BCR/ABL fusion gene, fewer than 20 percent blasts in the bone marrow and blood, myelodysplasia, and absence of PDGFRA or PDGFRB rearrangement. "Among the three members of TET family genes (TET1, TET2, and TET3), TET1 chromosome translocation and TET2 mutations have been identified in hematopoietic malignancies such as AML and chronic myelomonocytic leukemia (CMML)." (PMID 34885145, 2021).
colon adenoma (2 papers, 2021 to 2025). An adenoma that arises from the colon. "In contrast, Tet1-deficient and Tet1/TdgN151A double heterozygous ApcMin mice developed larger colonic adenomas with invasive characteristics." (PMID 40520993, 2025). "Further analysis revealed that colonic adenomas in Tet1 and Tdg mutant ApcMin mice exhibited reduced global DNA hypomethylation." (PMID 40520993, 2025).
Crohn disease (2 papers, 2024 to 2026). A gastrointestinal disorder characterized by chronic inflammation involving all layers of the intestinal wall, noncaseating granulomas affecting the intestinal wall and regional lymph nodes, and transmural fibrosis. "IFNγ+ ILC1s were accumulated in the intestine of Crohn’s disease patients with low expression levels of TET1 and TGFBR1." (PMID 38839760, 2024).
esophageal cancer (2 papers, 2019 to 2023). A primary or metastatic malignant neoplasm involving the esophagus. "The mRNA expression level of TET1 was significantly decreased in esophageal cancer cells and ESCC tissues; UTX demonstrated the similar expression level in esophageal cancer cells and ESCC tissues." (PMID 31804468, 2019).
Fanconi anemia (2 papers, 2021 to 2022). Fanconi anemia (FA) is a hereditary DNA repair disorder characterized by progressive pancytopenia with bone marrow failure, variable congenital malformations and predisposition to develop hematological or solid tumors. "By contrast to TET1 wild-type patients, TET1-mutated patients in the ICI-treated cohort were found to have a significantly increased mutation number of DDR pathways, including nucleotide excision repair (NER), Fanconi anemia (FA), homologous recombination (HR), and nonhomologous end joining (NHEJ)." (PMID 35395805, 2022).
hyperlipidemia (2 papers, 2021 to 2024). "Moreover, we investigated whether FFAs affected leptin expression and TET1 expression in PA-treated rat MSCs during adipogenic differentiation, to further substantiate the reprogramming of leptin in adipose tissue by intrauterine hyperlipidemia." (PMID 33431976, 2021).
hypopharyngeal cancer (2 papers, 2018 to 2019). Carcinoma, predominantly squamous cell, arising from the epithelial cells of the hypopharynx. "TET1 was methylated in 34 (59.6%), TET2 in 5 (8.8%), and TET3 in 15 (26.3%) of the 57 hypopharyngeal cancers examined." (PMID 29849955, 2018).
ischemia (2 papers, 2011 to 2024). A hypoperfusion of the BLOOD through an organ or tissue caused by a PATHOLOGIC CONSTRICTION or obstruction of its BLOOD VESSELS, or an absence of BLOOD CIRCULATION. "We hypothesize that TET-1 mice may induce more severe ischemia-related cellular damages and edema in retina after retinal ischemia induced by OA occlusion." (PMID 22053184, 2011). "The results further proved that over-expression of endothelial ET-1 in Hm TET-1 mice may promote water accumulation and edema in the glial cells of inner retina, leading to more severe neuronal cell death after ischemia and reperfusion." (PMID 22053184, 2011).
myeloid leukemia (2 papers, 2017 to 2022). A clonal proliferation of myeloid cells and their precursors in the bone marrow, peripheral blood, and spleen. "Plausible scenarios are that Tet1 is poorly expressed in differentiated cells, is required for the progression of myeloid leukemia, or both." (PMID 28408905, 2017). "Curiously, however, mice lacking Tet1 alone, or both Tet1 and Tet2, developed B cell rather than myeloid leukemias with relatively long latency (12–15 months)." (PMID 28408905, 2017). "Tet1 behaves as a weak tumor suppressor in B cells but may be weakly oncogenic in HSPC, where it promotes the development of myeloid leukemia in the absence of Tet2." (PMID 28408905, 2017).
neuropathic pain (2 papers, 2023 to 2025). Chronic pain caused by damage to nerve fibers. "In contrast, increased methylation levels and mRNA levels of TET1 and TET3 were linked to augmented pain hypersensitivity and allodynia in inflammatory and neuropathic pain models." (PMID 37108466, 2023). "In the current study, we investigated the role of DRG TET1 in OXA-induced neuropathic pain." (PMID 39864621, 2025).
Osteopenia (2 papers, 2018 to 2019). Osteopenia is a term to define bone density that is not normal but also not as low as osteoporosis. "Here we show that depletion of Tet1 and Tet2 results in impaired self-renewal and differentiation of bone marrow MSCs (BMMSCs) and a significant osteopenia phenotype." (PMID 29858571, 2018). "The depletion of Tet1 and Tet2 may lead to hypermethylation of the P2rX7 promoter to block miR-297a-5p, miR-297b-5p, and miR-297C-5p release, leading to downregulation of Runx2 signaling and osteopenia phenotype." (PMID 29858571, 2018). "In conclusion, depletion of Tet1 and Tet2 results in BMMSC impairment and an osteopenia phenotype." (PMID 29858571, 2018).
osteoporosis (2 papers, 2019 to 2023). A condition of reduced bone mass, with decreased cortical thickness and a decrease in the number and size of the trabeculae of cancellous bone (but normal chemical composition), resulting in increased fracture incidence. "Instead, as demonstrated in tet1 and tet2 knockout mice, it was likely that during aging the osteopenic phenotype is ascribable to a hypermethylation in Tet1 and Tet2 that leads osteoporosis by inhibiting the expression of Runx2." (PMID 37190071, 2023). "Given that both TET1 and TET2 are severely reduced in osteoporosis, pharmacological re-induction of TET1/TET2 may be of therapeutic benefit to individuals suffering from age-related bone loss or osteoporosis." (PMID 30606231, 2019). "Finally, in a mouse model of ovariectomy-induced osteoporosis, the numbers of clonogenic BMSC were dramatically diminished corresponding to lower trabecular bone volume and reduced levels of TET1, TET2 and 5hmC." (PMID 30606231, 2019). "Moreover, both TET1 and TET2 transcript levels were shown to be downregulated during osteoporosis." (PMID 30606231, 2019). "Moreover, we discovered that the expression of TET1 and TET2 is grossly deregulated in osteoporosis leading to deregulated 5hmC levels on promoters of genes controlling stem cell renewal and lineage determination in osteoporosis." (PMID 30606231, 2019).
ovarian tumor (2 papers, 2017 to 2019). "Our gain- and loss-of-function studies demonstrated that TET1 expression inhibits ovarian tumor growth and promotes apoptosis in vivo, while TET1 inhibition in tumor cells promotes tumor growth in vivo." (PMID 29156803, 2017). "TET3 is up-regulated in ovarian tumors, while TET1 doesn’t change." (PMID 31656201, 2019).
parathyroid carcinomas (2 papers, 2016 to 2018). "Recently, we have shown that in parathyroid carcinomas undetectable/low levels of 5hmC is associated with aberrant expression of TET1 and TET2 and that both genes have cell growth regulatory roles in parathyroid tumor cells." (PMID 30045709, 2018). "Here, we have performed novel experiments to determine the 5hmC level and TET1 protein expression in 43 parathyroid adenomas (PAs) and 17 parathyroid carcinomas (PCs) from patients who had local invasion or metastases and to address a potential growth regulatory role of TET1." (PMID 26973719, 2016).